INS (insulin)
Diseases named in the same sentence as INS in open-access papers (continued):
Sharing a sentence is not in itself a finding about the gene and the disease.
type 1 diabetes (continued). "Type 1 diabetes (T1DM) develops in childhood and adolescence and requires lifelong insulin injections for survival." (PMID 36419111, 2022). "The only study conducted on patients in the context of diabetes research showed that type 1 diabetes (T1D) patients have decreased serum TFF3 levels compared to healthy controls, which increased after insulin treatment." (PMID 36013467, 2022). "Higher affinity GADA predicts progression to type 1 diabetes, and in LADA predicts requirement of early insulin treatment." (PMID 34272582, 2021). "Automated insulin delivery systems and continuous glucose monitoring (CGM) are transforming type 1 diabetes management and improving glycemic outcomes." (PMID 33628834, 2021). "The Fuzzy Logic Automated Insulin Regulation (FLAIR) study directly compared the Medtronic 670G with the AHCL system in adolescents and young adults with type 1 diabetes." (PMID 33550442, 2021). "A version of this model, trained on data from patients with type 1 diabetes, is approved by the Food and Drug Administration, FDA, for replacement of animal experiments in the approval of the algorithm inside new insulin pumps." (PMID 34140893, 2021). "The occurrence of autoantibodies (AAb) to islet cell antigens is an established sign of the development of an autoimmune response directed against insulin-producing β-cells and characterizes the onset of the preclinical stage of type 1 diabetes mellitus (T1DM)." (PMID 34796016, 2021). "The aim of this retrospective study was to assess insulin requirements and CHO/IR in well-trained normal weight, overweight and obese pregnant women with type 1 diabetes across early, middle, and late pregnancy." (PMID 33732212, 2021). "The treatment of type 1 diabetes (T1D) is rapidly evolving with the development of novel technologies such as continuous subcutaneous insulin infusion (CSII), continuous glucose monitoring (CGM), sensor augmented pumps (SAP) and hybrid closed‐loop (HCL) systems." (PMID 34277976, 2021). "Type 1 diabetes mellitus (T1DM) is generally believed to be a chronic autoimmune disease characterised by the destruction of insulin-producing β-cells that results from a complex interaction between genetic susceptibility, immunological factors and environmental agents." (PMID 35144715, 2021). "Also, in type 1 diabetes, insulin and thyroid hormones may both be affected by autoimmunity." (PMID 34010957, 2021). "Patients with type 1 diabetes are often exposed to healthcare facilities for follow-up visits and prescription refills, and they frequently receive subcutaneous insulin injections, though the correlation of the subcutaneous insulin injection and MRSA colonization or infection remains unclear." (PMID 34203580, 2021). "Insulin pumps have been extensively studied as an alternative to multiple daily injections (MDI), particularly in pediatric patients for the management of insulin-dependent diabetes." (PMID 34064129, 2021). "For example, in at-risk children, oral insulin administration has previously failed to prevent type 1 diabetes, speculatively due to a suboptimal dose level or unclear effects across risk-specific subgroups, including those defined by insulin gene polymorphisms." (PMID 33595677, 2021). "Moreover, the Coronary Artery Calcification in Type 1 Diabetes cohort study found that type 1 diabetes affected adipose and skeletal muscle insulin sensitivity to a greater extent in women than in men, which might have contributed to the greater relative increase in cardiovascular risk in women." (PMID 33435964, 2021). "The primary aim of this study was to assess insulin requirements and carbohydrate to insulin ratio (CHO/IR) in normal weight, overweight, and obese pregnant women with type 1 diabetes across early, middle, and late pregnancy." (PMID 33732212, 2021). "However, it is uncertain whether or not type I diabetes (loss of insulin) induces the relocation of CD36 and resultant FA metabolism in the heart." (PMID 34940639, 2021).
type 1 diabetes (continued). "Type 1 diabetes mellitus (T1DM) is a disorder characterized by pancreatic dysfunction and β-cell death, ultimately resulting in a dysregulation of the glucose-insulin axis." (PMID 34681648, 2021). "In human type 1 diabetes (T1D) pancreatic islets, fasting conditions reduce PKA and mTOR activity and induce Sox2 and Ngn3 expression and insulin production." (PMID 34067055, 2021). "Type 1 diabetes mellitus (T1D) is a multifaceted chronic and progressive autoimmune syndrome that results in the functional impairment as well as the physical eradication of pancreatic insulin-producing beta cells." (PMID 33776903, 2021). "Type 1 diabetes (T1D) is one of the most prevalent early-onset autoimmune diseases, and numerous treatment regimens have been developed over the years with a mainstay focus on insulin injections, infusions, and pumps." (PMID 35004071, 2021). "The aim of this study was to explore the impactof real-world, off-label, patient controlled CGM use in combination withcontinuous subcutaneous insulin infusion (CSII) on costs and effects inpatients with type 1 diabetes in a Swedish clinic." (PMID 32517514, 2021). "Type 1 diabetes (T1DM) is an autoimmune disease in which beta cells are completely destroyed, resulting in metabolic dysfunction as a consequence of insufficient circulating levels of insulin." (PMID 34176167, 2021). "It is suggested that these “dual expressors” (DE) are increased in frequency in type 1 diabetes and that in people with type 1 diabetes there is a public BCR which can stimulate insulin-reactive CD4+ T cells." (PMID 34659258, 2021). "However, complete independence from exogenous insulin will be obtained only by biological approaches that foresee the replacement of functional beta cells obtained from stem cells: this will be a major challenge but the biggest hope for the subjects with type 1 diabetes." (PMID 33755854, 2021). "These clinical benefits have contributed to increase in insulin pump use from 57% to 63% and in CGM use from 7% to 30%, over a six to eight-year period in persons with type 1 diabetes." (PMID 33628834, 2021). "Steamed ginger extract was recently proven to have anti-hyperglycemic efficacy in alloxan-induced type 1 diabetic mice by closing KATP channels in pancreatic β cells and subsequent stimulation of insulin secretion." (PMID 34054538, 2021). "Both endocrine and exocrine tissue are affected in type 1 diabetes (T1D), but the disease is characterized by a chronic autoimmune destruction of insulin-producing beta cells." (PMID 34179094, 2021). "In type 1 diabetes, the main concern is DKA with the occurrence of suboptimal thiamine levels even prior to insulin therapy." (PMID 34309858, 2021). "Therefore, it was hypothesized that alefacept might prolong the preservation of endogenous insulin secretion by the remaining beta-cells in new-onset patients by changes in effector T cells, The Immune Tolerance Network Type 1 Diabetes with Alefacept (TIDAL) study." (PMID 32872668, 2020). "Type 1 diabetes mellitus (T1DM) is a chronic condition whereby one’s immune system attacks the pancreas, rendering it unable to produce adequate insulin for glucose entry from the circulation and into the cells of the body to fuel metabolism." (PMID 32865502, 2020). "One relates to the demonstration of important actions by ghrelin during the CRR to insulin-induced hypoglycemia, now newly shown using the STZ model of type 1 diabetes." (PMID 33042003, 2020). "Interestingly, it may also increase serum insulin levels in mice with type 1 diabetes." (PMID 33153226, 2020). "In type 1 diabetic mice, JAM2 and JAM3 have been reported to polarize leukocyte trans-endothelial migration and subsequently destruct insulin-producing beta cells in the pancreas." (PMID 32932992, 2020). "An oral insulin formulation, hexyl-insulin monoconjugate 2 (HIM2), conjugated to PEG and a PE via an amide bond at Lys-β29 has been tested for its ability to treat type I diabetes mellitus." (PMID 33352795, 2020).
type 1 diabetes (continued). "We had information on islet autoantibodies (towards insulin, glutamic acid decarboxylase, and IA2) at diagnosis from 76% the children who developed type 1 diabetes, and 92% were positive for at least one islet autoantibody." (PMID 32119659, 2020). "Type I diabetes (T1DM) is a chronic autoimmune condition characterized by progressive β-cell destruction and insufficient insulin production." (PMID 33272321, 2020). "To validate the essential role of L. mesenteroides EH-1 in regulation of glucose and insulin levels in diabetic mice, we fed STZ-induced type 1 diabetic mice with heat-killed L. mesenteroides EH-1." (PMID 32404878, 2020). "Insulin is a key autoantigen in Type 1 Diabetes (T1D), targeted by both T and B cells." (PMID 33262765, 2020). "The Type 1 Diabetes Prediction and Prevention study (DIPP) investigated whether nasal insulin could reduce the incidence of T1D." (PMID 32204344, 2020). "All four major autoantibodies, specific for GAD (GADA), islet antigen-2 (IA-2A), insulin (IAA) and zinc transporter 8 (ZnT8A), were found in these slow progressors to type 1 diabetes (hereafter referred to as ‘slow progressors’)." (PMID 32157332, 2020). "Insulin replenishment is the most common treatment for type 1 diabetes (T1D)." (PMID 30670068, 2019). "TMSCs can also be efficiently differentiated into functional insulin-producing cells, and administration of these cells into streptozotocin (STZ)-induced type 1 diabetic mice improved glucose intolerance." (PMID 31018536, 2019). "In type 2 and type 1 diabetes mouse models, FMD cycles successfully restored insulin secretion and glucose homeostasis following the generation of insulin-producing β-cells, with a gene expression profile resembling that observed during pancreatic development." (PMID 31728501, 2019). "In the type 1 diabetic mouse model in vivo, the AuNC-PBA-Ins complex effectively released insulin and regulated blood glucose level in the normoglycemic state for up to 3 days." (PMID 31159842, 2019). "The autoantibodies against glutamic acid decarboxylase (GADA), insulinoma antigen-2 (IA-2A), insulin (IAA), and zinc transporter-8 (ZnT-8A) comprise the most reliable biomarkers for type 1 diabetes in both children and adults." (PMID 31827651, 2019). "In order to manage the autoimmune destruction of insulin-producing pancreatic beta cells in type 1 diabetes (DM1), it is necessary to administer insulin via lifelong daily injection." (PMID 31798448, 2019). "In type-I diabetes (T1DM), the β-cells of the islets of Langerhans in the pancreas responsible for producing insulin are lost, typically from an attack from the immune system, causing an insulin deficiency in the body." (PMID 30671675, 2019). "At present, there are limited data for CGM use in type 1 diabetes managed with MDI, the most common insulin therapy used in clinical practice." (PMID 29273897, 2018). "In children with type 1 diabetes mellitus (T1DM), this level of physical activity can benefit glycaemic control, insulin sensitivity, protect against cardiovascular disease, and improve body composition, quality of life and lifelong health." (PMID 29415687, 2018). "Type I diabetes (T1DM), characterized by the need for daily administration of insulin, results from autoimmune destruction of insulin-producing pancreatic β-cells." (PMID 30065848, 2018). "Type 1 diabetes (DM1) is one of the most common chronic diseases in childhood and requires life-long insulin therapy and continuous health care support." (PMID 29954380, 2018). "The trial involved 96 adults with type 1 diabetes and IAH, randomised in a 2 × 2 factorial design to CGM, insulin pumps or multiple daily injections alone." (PMID 28660491, 2018). "In human type 1 diabetes pancreatic islets, fasting conditions reduce PKA and mTOR activity and induce Sox2 and Ngn3 (Neurogenin 3) expression and insulin production." (PMID 29480368, 2018).
type 1 diabetes (continued). "Emerging technologies in the treatment of type 1 diabetes in pregnancy including CGM, insulin pumps and most recently sensor-integrated insulin delivery show promise in the management of this challenging condition." (PMID 29383544, 2018). "To identify type 1 diabetes patients who might benefit most from a standardized environment we investigated potential predictors of metabolic improvement such as age, sex, BMI, waist circumference, HbA1c, fasting BG, total daily insulin dose, LDL/HDL ratio, and duration of disease." (PMID 29529063, 2018). "Type 1 diabetes is a multifactorial autoimmune disorder triggered by islet antigen-specific CD4+ and CD8+ T cell-mediated destruction of insulin-producing cells in the pancreas." (PMID 29881878, 2018). "In addition, different from type 1 diabetes, high autophagy does not cause islet destruction; instead, β cell mass expands in autophagy-hyperactive mice, possibly due to a compensatory effect of reduction in insulin contents." (PMID 29898399, 2018). "A trial conducted in subjects with type 1 diabetes indicated that a metformin add-on CSII therapy resulted in an improvement in blood glucose control and insulin requirements." (PMID 29946148, 2018). "Type 1 diabetes mellitus (T1DM) is a chronic metabolic disease, characterized by hyperglycemia, which develops when the pancreas stops producing insulin due to auto-immune destruction of the β cells." (PMID 30482202, 2018). "In this regard, insulin promotes the expression of DNA methyltransferases leading to methylation resulting in atherosclerosis, broadening the research field of CAD in type 1 diabetes." (PMID 29695241, 2018). "Furthermore, we argue that accepting ABCD as a diagnosis will be critical in order to accelerate pharmaceutical, academic and public activities leading to clinical trials that could reverse beta cell autoimmunity and halt progression to symptomatic insulin-requiring type 1 diabetes." (PMID 27785529, 2017). "Type 1 diabetes (T1DM) requires intensive self-monitoring of blood glucose and self-management, including administering insulin, regulating diet and exercise, to maintain optimal glycaemic control." (PMID 29258565, 2017). "In the Sweet Talk study, that also aimed to improve glycemic control among Type 1 diabetics, intervention participants received daily SMS messages on insulin injections, blood glucose testing, healthy eating, and exercise." (PMID 29258499, 2017). "However, it may have important clues to offer in terms of estimating the occurrence of hypoglycemia unawareness in patients with type 1 diabetes receiving insulin therapy, while the meal times, wake-up times, and bedtimes may have differed from one patient to another in this study." (PMID 28683068, 2017). "Clinical trials in type 1 diabetes showed that adequate dosing of anti-CD3 resulted in improved C-peptide responses and reduced exogenous insulin need." (PMID 28450863, 2017). "In type 1 diabetes, the single large intervention trial (DCCT) and post-trial follow up (EDIC) compared intensive versus conventional insulin therapy and showed a reduction in CVD with intensive glycemic treatment in the long-term follow-up study." (PMID 27188479, 2016). "For example, presence of autoantibodies against insulin, GAD65, and IA-2 can confirm the diagnosis of type I diabetes (T1D), and anti-dsDNA antibodies bind to resident kidney cells and trigger signaling that promotes inflammation and fibrosis in SLE." (PMID 26997761, 2016). "Type 1 diabetes mellitus (T1DM) occurs in childhood and is characterized by T-cell autoimmune disease mediated destruction of insulin secreting β cells in the pancreatic islets." (PMID 27019854, 2016). "Type 1 diabetes mellitus (T1DM) is believed to be an autoimmune disease where the immune system attacks pancreatic β-cells in islets and abolish endogenous insulin production." (PMID 27110577, 2016).
type 1 diabetes (continued). "Management of type 1 diabetes involves the completion of multiple daily adherence behaviors that may be complex and often disruptive to daily life (e.g., blood glucose checking at least four times per day, correctly calculating, and administering insulin doses)." (PMID 27610391, 2016). "Whether this same expansion without loss of insulin expression can be demonstrated for other hESC lines or iPSCs remains to be determined as well as the number of hESCs derived β-cells to effectively ameliorate type 1 diabetes in humans." (PMID 28702240, 2016). "Proteins such as insulin in the pancreatic islet are in immediate proximity or, as constituents of β cells, even contribute to the structure of the TLO in type 1 diabetes." (PMID 27881983, 2016). "The proportion of subjects prescribed insulin or insulin analogs alone (ATC code A10A), indicating type 1 diabetes, was 0.1% (n=2) in the obese cohort and 0.7% (n=54) in the comparison group (P<0.01)." (PMID 27548712, 2016). "Therefore, we conclude that hyperexpression of HLA-I is a characteristic feature of islets in human type 1 diabetes, usually linked to remaining insulin, and that it is not an artefact unique to any particular geographical region, mode of tissue preservation or mechanism of pancreas retrieval." (PMID 27506584, 2016). "Continuous subcutaneous insulin infusion (CSII) is an effective therapy to minimize hypoglycemia and maintain long-term glycemic control in type I diabetes patients." (PMID 26037035, 2015). "These predictive scores performed well in identifying type 1 diabetes, suggesting that professional CGM is useful for identifying type 1 diabetes in insulin users." (PMID 25621692, 2015). "In the present study, we investigated separate and combined treatment effects of crocin and ZnCl2 on blood levels of zinc, glucose, insulin, malodialdehyde (MDA), and total antioxidant capacity (TAC) in streptozotocin (STZ)-induced type 1 diabetic rats." (PMID 26468459, 2015). "Differently from type 1 diabetes, LADA shows a slower progression towards β-cell failure and insulin requirement and higher levels of insulin resistance." (PMID 26252955, 2015). "In patients with type 1 diabetes, co-transplantation of ASC-derived insulin-secreting islets with hematopoietic stem cells decreased exogenous insulin requirement, increased c-peptide levels, and prevented ketoacidosis." (PMID 26519255, 2015). "Interestingly, LRP1 expression is downregulated in brain capillaries of streptozotocin-injected mice and CSF soluble LRP1 is increased in type 1 diabetes patients treated with insulin for several years, suggesting that insulin might increase central LRP1, at least on the long term." (PMID 26136681, 2015). "We show that insulin reactivity by a CD8+ T-cell clone, known to induce type 1 diabetes, is characterized by weak T-cell antigen receptor binding to a relatively unstable peptide-MHC." (PMID 26085090, 2015). "Patients with concomitant type 1 diabetes and PAI are commonly reported to have reduced insulin requirement and some guidelines have suggested that longer acting GCs such as prednisolone be used in this setting." (PMID 26500000, 2015). "Thus, based on the stimulatory property of arecoline, we attempted to investigate whether arecoline can restore the serum insulin and testosterone levels in experimentally induced type 1 diabetic rats, where low serum insulin levels deregulate the gonadal and prostate physiology." (PMID 25695047, 2015). "Oral administration of the CTB subunit coupled with insulin or the GAD35 autoantigen was shown to induce immunological tolerance and suppression of type 1 diabetes in NOD mice." (PMID 26378585, 2015). "In patients with type 1 diabetes both fasting LPS and LPS-AUC correlated with CRP (fasting r = 0.428; p = 0.009, AUC r = 0.338; p = 0.044) and insulin dose (fasting r = 0.479; p = 0.004, AUC r = 0.528; p = 0.001)." (PMID 24959195, 2014).